ENSG00000273025 (novel transcript)
Gene: Protein-coding gene on chromosome 15 (72,266,746 to 72,319,946, reverse strand). Ensembl gene ENSG00000273025.
Genetic constraint (gnomAD): Missense variants: 536 observed, 550.79 expected, observed/expected ratio (o/e) 0.97, 90% interval 0.91 to 1.04. Synonymous variants: 291 observed, 239.4 expected, observed/expected ratio (o/e) 1.22, 90% interval 1.1 to 1.34.